CHERP (calcium homeostasis endoplasmic reticulum protein)
Description:
Involved in calcium homeostasis, growth and proliferation.
Synonyms: SCAF6; ERPROT213-21; DAN16
Tractability: PROTAC: UniProt records ubiquitination sites on it; ubiquitination databases record sites on it; its protein half-life has been measured.
Gene: Protein-coding gene on chromosome 19 (16,517,882 to 16,542,448, reverse strand). Ensembl gene ENSG00000085872.
Subcellular location: Cytoplasm; Cytoplasm, perinuclear region; Endoplasmic reticulum
Pathways (Reactome):
Metabolism of RNA: mRNA Polyadenylation; mRNA Splicing - Major Pathway
Chromatin organization: CHD1 and CHD2 subfamily
Disease: Dengue Virus-Host Interactions
Gene Ontology:
Molecular function: protein binding; RNA binding; transmembrane transporter binding; nucleic acid binding
Biological process: intracellular calcium ion homeostasis; negative regulation of cell population proliferation; positive regulation of calcineurin-NFAT signaling cascade; release of sequestered calcium ion into cytosol; nervous system development; RNA processing
Cellular component: cytoplasm; endoplasmic reticulum; membrane; perinuclear region of cytoplasm; nucleoplasm; sarcoplasmic reticulum membrane
Genetic constraint (gnomAD): Loss-of-function variants: 8 observed, 94.75 expected, observed/expected ratio (o/e) 0.0844, 90% interval 0.049 to 0.15. The upper end of that interval is the gene's LOEUF score, 0.15, which puts it in group 1 of 6, group 1 being the genes least tolerant of losing a copy. Missense variants: 884 observed, 1,167.7 expected, observed/expected ratio (o/e) 0.76, 90% interval 0.71 to 0.8. Synonymous variants: 559 observed, 479.61 expected, observed/expected ratio (o/e) 1.17, 90% interval 1.09 to 1.25.
Homologues: Orthologues: chimpanzee CHERP (100% identical), macaque CHERP (99% identical), dog CHERP (98% identical), pig CHERP (98% identical), guinea pig CHERP (96% identical), mouse Cherp (95% identical), rat Cherp (95% identical), tropical clawed frog cherp (82% identical), zebrafish cherp (73% identical), rabbit CHERP (55% identical), Drosophila melanogaster scaf6 (37% identical), Caenorhabditis elegans tag-65 (21% identical).
Diseases named in the same sentence as CHERP in open-access papers:
CHERP is named in the same sentence as 8 diseases in open-access papers, as found by Europe PMC text mining. Sharing a sentence is not in itself a finding about the gene and the disease. The quoted sentences say what the papers report.
breast carcinoma (1 paper, 2017). "Most importantly, there are several genes that can distinguish the four breast cancer subtype as specific therapeutic targets for each subtype, including EFCAB2 for luminal A, ATG16L2 for luminal B, C1QTNF6 and NDUFS6 for HER2+, as well as CHERP, TIAM1, and GABRP for TNBC." (PMID 28245581, 2017).
erythroleukemia (1 paper, 2018). Acute erythroid leukemia characterised by the presence of at least 50% erythroid precursors and at least 20% myeloblasts in the bone marrow. "CHERP (named after “calcium homeostasis and endoplasmic reticulum protein”) was first reported as an ER-transmembrane protein regulating Ca2+ homeostasis in human erythroleukemia (HEL) and Jurkat T cells." (PMID 29463029, 2018).
neuroblastoma (1 paper, 2017). Neuroblastoma (NB) is the most common solid, extracranial childhood tumor. "To investigate whether aberrant CHERP expression is associated with the prognosis of neuroblastoma patients, we used the Tumor Neuroblastoma public database (available from the online R2: Genomics Analysis and Visualization Platform)." (PMID 29113358, 2017). "Furthermore, we analyzed whether CHERP expression levels were associated with MYCN expression in neuroblastoma patients." (PMID 29113358, 2017). "In this study, we observed that calcium homeostasis endoplasmic reticulum protein (CHERP) was involved in the maintenance of neuroblastoma cell proliferation and tumorigenicity." (PMID 29113358, 2017). "Here, we verified that CHERP is located in the nuclei in neuroblastoma cells and revealed its role in controlling cell proliferation and apoptosis during neuroblastoma initiation and development." (PMID 29113358, 2017). "We found that the levels of AKT, mTOR and 4E-BP1 phosphorylation were attenuated after CHERP depletion, which indicated that the AKT/mTOR/4E-BP1 pathway was involved in neuroblastoma cell apoptosis mediated by CHERP depletion." (PMID 29113358, 2017). "Here, we show that calcium homeostasis endoplasmic reticulum protein (CHERP) is involved in neuroblastoma cell proliferation, apoptosis and tumorigenicity." (PMID 29113358, 2017). "Taken together, these experiments indicate that CHERP plays a key role in the colony-forming ability and tumorigenicity of neuroblastoma." (PMID 29113358, 2017). "To confirm the definitive localization of CHERP in neuroblastoma cells, we extracted nuclear and cytoplasmic proteins and used western blot assays to determine the precise location of CHERP." (PMID 29113358, 2017). "Additional functional studies showed that CHERP knockdown inhibited neuroblastoma cell proliferation in vitro and resulted in defective tumorigenicity in vivo." (PMID 29113358, 2017). "In conclusion, higher CHERP expression is markedly associated with poor overall survival in neuroblastoma patients, which indicates that CHERP is a prognostic marker for neuroblastoma." (PMID 29113358, 2017). "To confirm this observation, we used data from the Neuroblastoma Prognosis Database, and the Kaplan–Meier analysis revealed that high CHERP expression was prognostic for poor outcomes in the Oberthuer Lab and Seeger dataset." (PMID 29113358, 2017). "Here, we determined that CHERP expression was a potential prognostic marker in neuroblastoma patients." (PMID 29113358, 2017). "In brief, we reveal that the down-regulation of CHERP induces apoptosis in neuroblastoma cells by activating the ATF4/CHOP/DR5 signaling axis and inhibiting the AKT/mTOR signaling pathway." (PMID 29113358, 2017). "In conclusion, these results indicate that ER stress is involved in neuroblastoma cell apoptosis induced by CHERP depletion; moreover, up-regulation of DR5 and inhibition of the AKT/mTOR/4E-BP1 pathway represent two separate downstream events of this process." (PMID 29113358, 2017). "Overall, our findings provide new insights into the mechanism whereby CHERP regulates neuroblastoma cell fate and provides a potential therapeutic target for neuroblastoma." (PMID 29113358, 2017). "Moreover, CHERP expression was associated with patient age, cause of death and stages and MYCN status of neuroblastoma patients." (PMID 29113358, 2017). "Thus far, we have shown that CHERP depletion can induce neuroblastoma cell apoptosis and increase the expression of cleaved caspase-3 and cleaved caspase-8 expression." (PMID 29113358, 2017). "Moreover, CHERP depletion suppressed neuroblastoma cell proliferation by inducing endoplasmic reticulum stress and cell apoptosis." (PMID 29113358, 2017). "Moreover, CHERP depletion combined with Dox treatment confirmed that CHERP plays an important role in the survival and drug resistance of neuroblastoma cells." (PMID 29113358, 2017).
neuroblastoma (continued). "Considering the functional roles of CHERP in neuroblastoma development and maintenance, CHERP might function as a novel therapeutic target for neuroblastoma patients." (PMID 29113358, 2017). "Furthermore, our in vitro and in vivo experimental results demonstrate that the status of CHERP is essential for clone forming ability and tumorigenicity of neuroblastoma cells." (PMID 29113358, 2017). "To investigate whether CHERP depletion could affect tumorigenicity in neuroblastoma cells, we performed a soft-agar colony-formation assay." (PMID 29113358, 2017). "Our discovery of the functions of CHERP in neuroblastoma cell proliferation, apoptosis and tumorigenicity combined with integrated drug treatments may provide a new potential strategy for clinical treatment of neuroblastoma." (PMID 29113358, 2017). "Therefore, we investigated whether depleting CHERP could affect the response of neuroblastoma to doxorubicin (Dox) treatment." (PMID 29113358, 2017). "Further mechanistic studies revealed that CHERP depletion induces ERS and CHOP-dependent DR5 transcription; attenuates AKT, mTOR and 4EBP1 phosphorylation; and ultimately promotes neuroblastoma cell apoptosis." (PMID 29113358, 2017). "In brief, CHERP depletion induces ER stress and CHOP-dependent DR5 transcription, attenuates mTOR and 4EBP1 phosphorylation, and ultimately induces neuroblastoma cell apoptosis." (PMID 29113358, 2017). "We speculated that CHERP depletion leads to ERS and inhibits neuroblastoma initiation and that tumor progression is related to the subcellular localization of CHERP in cells." (PMID 29113358, 2017).
nonalcoholic fatty liver disease (1 paper, 2025). "In another study which aimed to identify genes associated with nonalcoholic fatty liver disease, CHERP was shown to be strongly downregulated in afflicted individuals, but not much is known about its potential involvement in disease development so far." (PMID 41163109, 2025).
tumor (1 paper, 2017). "Moreover, based on the Versteeg dataset, CHERP was expressed significantly more highly in the overall death, older age (>18 month) and tumor-caused death groups than in the control group." (PMID 29113358, 2017). "CHERP depletion impaired tumor growth compared with that in the GFPsi group, and mice injected with CHERPsi-2# cells did not form xenograft tumors **P < 0.001." (PMID 29113358, 2017). "Moreover, high CHERP expression significantly correlated with advancing tumor stage in the data extracted from the Kocak and Versteeg datasets." (PMID 29113358, 2017). "Because apoptosis may reduce cell proliferation and inhibit tumor growth, we detected nuclear condensation in CHERP-depleted cells using Hoechst 33258 staining." (PMID 29113358, 2017). "To date, the role of CHERP in tumor biology remains unclear." (PMID 29113358, 2017).
CHERP also shares sentences with these, for which no sentence is quoted: cancer (1 paper); osteoporosis (1); tauopathy (1).